REG3A (regenerating family member 3 alpha)
Diseases named in the same sentence as REG3A in open-access papers (continued):
Sharing a sentence is not in itself a finding about the gene and the disease.
hepatocellular carcinoma (5 papers, 2019 to 2022). A malignant tumor that arises from hepatocytes. "REG4 is overexpressed in colorectal and gastric carcinomas whereas REG3A is expressed in hepatocellular carcinomas with β-catenin mutations." (PMID 31696115, 2019). "Further siRNA-mediated loss-of-function experiments showed that silencing Reg3A expression could inhibit the invasion and migration of hepatocellular carcinoma, which were detected using wound healing assay and 24-well transwell assay." (PMID 31921694, 2019). "In particular, there are a growing number of publications focusing on the function of Reg3A in human cancers, including GC, pancreatic cancer, colorectal cancer, hepatocellular carcinoma, and glioma." (PMID 34605357, 2021). "• Reg3A mRNA expression was induced by activation of β-catenin in the Huh7 hepatoma cell line, and this induced expression was abolished by siRNA interference directed against β-catenin." (PMID 31921694, 2019). "In hepatoma cells, REG3A mRNA expression could be gradually induced after 72 h of lithium chloride (LiCl) treatment, and β-catenin siRNA effectively inhibited REG3A expression in cells treated with LiCl." (PMID 34811636, 2022). "In human hepatocellular carcinomas (HCC), tumor-stroma crosstalk enhanced REG3A expression and significantly increased the proliferation of HCC cells via the p42/44 pathway/PDGF-ββ signaling." (PMID 34811636, 2022). "Reg3a is absent in normal adult hepatocytes, most likely due to a silencer region in its promoter that is inactive in hepatoma cells." (PMID 31696115, 2019). "In a study of 265 surgically resected unifocal primary hepatocellular carcinomas, Reg3A was found to express in 97 (36.6%) samples, but not in any of 219 non-tumorous liver tissues." (PMID 31921694, 2019).
pancreatic ductal adenocarcinoma (5 papers, 2019 to 2025). An infiltrating adenocarcinoma that arises from the epithelial cells of the pancreas. "Notably, similar patterns of dysregulation are observed in inflammation-associated cancers, such as pancreatic ductal adenocarcinoma, gastrointestinal malignancies, and primary liver cancer, raising the possibility that REG3A could serve as a diagnostic or prognostic biomarker." (PMID 40723277, 2025). "In pancreatic ductal adenocarcinoma, REG3A was overexpressed in 79% (30/38) of pancreatic tissue samples and was correlated with nodal involvement, distant metastasis, and short survival." (PMID 34811636, 2022). "One pilot study reported the role of REG3A in modulating pancreatic ductal adenocarcinoma which interacts with WNT/CTNNB1 and TGF-beta pathways." (PMID 31940813, 2020). "A recent study analyzed the level of Reg3A in serum or plasma from 85 healthy donors or 166 patients with pancreatic ductal adenocarcinoma from three independent cohorts." (PMID 31921694, 2019). "Reg3A was found over-expressed in 79% (30/38) of pancreatic tissues from Japanese individuals with pancreatic ductal adenocarcinoma." (PMID 31921694, 2019). "In chronic colitis, gastrointestinal graft-versus-host disease (GI-GvHD), sepsis, and pancreatic ductal adenocarcinoma (PDAC), increased REG3A levels reflect heightened disease activity." (PMID 40723277, 2025).
psoriasis (5 papers, 2020 to 2024). An autoimmune condition characterized by red, well-delineated plaques with silvery scales that are usually on the extensor surfaces and scalp. "As a regenerating gene, REG3A was abundantly expressed in the lesional skin of psoriasis patients and in IL-17A-induced neonatal human epidermal keratinocytes (NHEKs); however, its expression was very low in differentiated NHEKs." (PMID 34811636, 2022). "In the lesional skin of psoriasis patients, skin injury can increase REG3A expression through IL-17/IL-17RA." (PMID 34811636, 2022). "After skin injury, REG3A promotes skin keratinocyte proliferation and wound re-epithelialization during normal wound repair and psoriasis." (PMID 34811636, 2022). "In keratinocytes, the expression of regenerating islet-derived protein 3-alpha (REG3A), an intestinal anti-microbial protein, is increased during psoriasis." (PMID 33132897, 2020). "IL-17A induces keratinocytes to express REG3A, and this process promotes the proliferation of keratinocytes after injury in psoriasis." (PMID 33132897, 2020). "On the other hand, REG3A is established to be highly expressed in skin cells in concert with IL-17 during psoriasis and wound healing, which might play a critical role in muscle tissue healing in PM/DM." (PMID 32153557, 2020).
acute pancreatitis (4 papers, 2020 to 2022). An acute inflammatory process that leads to necrosis of the pancreatic parenchyma. "Strong immunoreactivity to anti-human REG3A antibodies was found in sections of canine pancreas affected with acute pancreatitis, but it was weak in healthy pancreatic tissue." (PMID 36387376, 2022). "We previously produced recombinant Reg3α protein (rReg3α) and proved that it protects against acute pancreatitis in mice." (PMID 36142497, 2022). "Immunohistochemistry using anti-human REG3A antibodies showed a very strong immunoreactivity throughout pancreatic sections of a dog suffering from acute pancreatitis, but minimal, patchy immunoreactivity in histologically normal canine pancreas." (PMID 36387376, 2022). "Reg3a has been shown to regulate keratinocyte proliferation and differentiation after skin injury via Reg-Extl3-PI3K-Cyclin D1 pathway, while Reg3g downregulates the Stat3-Socs signaling which may result in enhanced apoptosis in acute pancreatitis." (PMID 34926699, 2021).
chronic pancreatitis (4 papers, 2016 to 2019). A chronic inflammatory process causing damage and fibrosis of the pancreatic parenchyma. "In the pancreatic juice of patients with pancreatic adenocarcinoma, the levels of Reg3A had been found to be elevated, approximately 24 times higher than in patients with other pancreatic diseases, 16 times higher than those with chronic pancreatitis." (PMID 31921694, 2019).
colon cancer (4 papers, 2016 to 2021). "Bioactivity of hIL-22 was confirmed by the secretion of interleukin 10 (IL-10) from the colon cancer derived epithelial cell line Colo205 and the secretion of Regenerating islet-derived protein 3 alpha (Reg3α) from human jejunal enteroids." (PMID 32582668, 2020). "Indeed, shRNA silencing of REG1CP reduced REG3A expression at both the transcript and protein levels in LIM1215 and HT-29 colon cancer cells that expressed relatively high levels of REG1CP among a panel of colon cancer cell lines." (PMID 31767869, 2019).
Sepsis (4 papers, 2022 to 2025). Sepsis is defined as life-threatening organ dysfunction caused by a dysregulated host response to infection. "In sepsis, REG3A has recently emerged as both a diagnostic and prognostic biomarker." (PMID 40723277, 2025).
type 2 diabetes (4 papers, 2015 to 2024). "Successively, short peptides derived from Reg3δ and Reg3α have been employed in clinical trials, showing favorable therapeutic effects in patients with type I and type II diabetes." (PMID 39857608, 2024). "This combined, with the good clinical safety profile of REG3A (ALF-5755) observed in a phase I study involving healthy volunteers and a phase II study in patients with acute liver failure, are major arguments for translational exploration of REG3A in patients with type 2 diabetes." (PMID 36918710, 2023). "For example, microarray studies performed on human pancreatic islets isolated from patients with type 2 diabetes and glucose-tolerant controls identified, among other changes, overexpression of ENPP1, TSPAN4, TSPAN8, CSRP1, REG3A and REG3G, genes that were also upregulated with age in our study." (PMID 26699651, 2016).
cystic fibrosis (3 papers, 2006 to 2022). Autosomal recessive disorder caused by pathogenic variants in the CFTR gene (cystic fibrosis transmembrane conductance regulator), which encodes a chloride and bicarbonate channel expressed in epithelial cells, and follow the diagnosis criteria. "In the nervous system, threads of REG1A and REG3A were found within neurofibrillary tangles and senile plaques of people with Alzheimer's disease, and more recently, REG3A has gained significance as an early marker for cystic fibrosis in neonates." (PMID 36387376, 2022). "The cystic fibrosis mouse pancreas has constitutively elevated expression of the Reg/PAP cell stress genes (60-fold greater Reg3α, and 10-fold greater PAP/Reg3β and Reg3γ)." (PMID 16700916, 2006).
Insulin resistance (3 papers, 2023 to 2025). Increased resistance towards insulin, that is, diminished effectiveness of insulin in reducing blood glucose levels. "We show that IL-22 and REG3A have opposite effects on fat accumulation in the liver and insulin resistance development despite inducing a similar shift in fecal microbiota composition." (PMID 41027972, 2025). "We showed that IL-22 and REG3A have opposite effects on fat accumulation in the liver and insulin resistance development despite inducing a similar shift in fecal microbiota composition." (PMID 41027972, 2025). "We show thus that IL22 and REG3A have opposite effects on fat accumulation in the liver and insulin resistance development despite inducing a similar shift in fecal microbiota composition." (PMID 41027972, 2025). "Interestingly, REG3A positive effects on hepatic steatosis are mitigated by elevated insulin resistance." (PMID 41027972, 2025). "This suggests that REG3A may enhance insulin action through an Akt-independent mechanism and thus contribute to curb the development of insulin resistance." (PMID 36918710, 2023).
liver cancer (3 papers, 2019 to 2025). An epithelial or non-epithelial malignant neoplasm that arises from the liver. "The earliest identified Reg3A-overexpressed gastrointestinal malignancy is liver cancer, so that Reg3A is also named as the encoded protein of genes expressed in heptocarcinoma-intestine-pancreas (HIP)." (PMID 31921694, 2019). "Although the expression of Reg3A was undetectable in normal and non-tumoral liver tissue, Reg3A mRNA was found expressed at a high level in the tumors of 7 of 29 (about 25%) human primary liver cancers." (PMID 31921694, 2019). "Although direct evidence linking REG3A-modulated microbiota to cancer is currently lacking, REG3A’s known ability to shape a beneficial microbial community and preserve epithelial integrity suggests a potential protective role, particularly in colorectal and liver cancers." (PMID 40723277, 2025).
liver disease (3 papers, 2015 to 2025). "This supports expectations that exogenous Reg3α might accumulate on such deposits and thereby act as an ECM-targeted antioxidant in human ALF and other hepatic disorders." (PMID 25938566, 2015).
Type 1 Diabetes (3 papers, 2022 to 2024). "Unlike that in normal human epithelial cells, the expression of REG3A and Reg3γ mRNA was significantly decreased in the skin of diabetic patients and streptozotocin (STZ)-induced experimental type 1 diabetic T1D mice, respectively." (PMID 34811636, 2022). "The defensin REG3A showed a slightly lower expression in children and subjects with recent onset Type 1 diabetes when compared with non-diabetic adults." (PMID 38717484, 2024).
AIDS (2 papers, 2020 to 2023). A syndrome resulting from the acquired deficiency of cellular immunity caused by the human immunodeficiency virus (HIV). "Conversely to the fungal translocation marker BDG and the gut damage marker REG3α, time of blood collection matters for the proper evaluation for LPS and I-FABP as markers for the risk of inflammatory non-AIDS co-morbidities." (PMID 32398104, 2020).
breast carcinoma (2 papers, 2022 to 2024). "Genetic techniques were employed to modify REG3A expression, and the resulting effects on the behaviors of breast cancer cells were examined." (PMID 38840145, 2024). "Knocking down or knocking out ZNF680 reduced REG3A expression, while its overexpression increased it in primary breast cancer cells." (PMID 38840145, 2024). "A constitutively active mutant S473D Akt1 (caAkt1) restored Akt-mTOR activation and counteracted the proliferation inhibition and apoptosis induced by REG3A knockdown in breast cancer cells." (PMID 38840145, 2024). "Additionally, enhanced binding between ZNF680 protein and the REG3A promoter was observed in breast cancer tissues and cells." (PMID 38840145, 2024).
cardiac sarcoidosis (2 papers, 2021 to 2022). Sarcoidosis affecting the tissues of the heart. "In order to clarify whether the formation of granulomata occurs via accumulation of chemoattracted macrophages we determined the regenerating islet-derived protein (Reg) family members Reg3A and Reg3γ in the myocardium of patients with cardiac sarcoidosis." (PMID 33923774, 2021). "The myocardial accumulation of monocyte/macrophage-derived OSM, along with the expression of Reg3A and Reg3γ in remodeling cardiomyocytes, emphasizes the prevalence of an OSM/OSMR/Stat3/Reg axis in the development of cardiac sarcoidosis." (PMID 33923774, 2021). "Moreover, reexpression of this non-muscle actinin and cardiac accumulation of Reg3A, Reg3, and OSM in patients with cardiac sarcoidosis correlate well with macrophage recruitment and granuloma formation." (PMID 35163735, 2022).
celiac disease (2 papers, 2021 to 2023). An autoimmune genetic disorder with an unknown pattern of inheritance that primarily affects the digestive tract. "REG3α has long been proposed as a biomarker of intestinal epithelial damage in multiple inflammatory diseases in which plasma REG3α levels are significantly elevated, such as CD, celiac disease, ulcerative colitis, nonalcoholic steatohepatitis, and gastrointestinal graft-versus-host disease." (PMID 37153621, 2023).
dermatomyositis (2 papers, 2020 to 2021). Dermatomyositis (DM) is a type of idiopathic inflammatory myopathy characterized by evocative skin lesions and symmetrical proximal muscle weakness. "In polymyositis and dermatomyositis, miR-146a, which targets regenerating family member 3 alpha (REG3A), restrains macrophage migration by lessening REG3A expression, sequentially weakening polymyositis and dermatomyositis." (PMID 34592882, 2021).
enteropathies (2 papers, 2021 to 2025). "In a comparative proteomic study using canine feces, dogs with chronic GID had higher concentrations of a REG3A/PAP homolog, which is likely the same protein as REG3E, than control dogs, but there was also some overlap, particularly between dogs with food-responsive enteropathies and healthy dogs." (PMID 40392915, 2025).
glioma (2 papers, 2020 to 2022). A benign or malignant brain and spinal cord tumor that arises from glial cells (astrocytes, oligodendrocytes, ependymal cells). "In glioma cells, REG3A functions as a downstream target gene of lncRNA RHPN1-AS1 and participates in the proliferation, migration, and invasion activity regulated by lncRNA RHPN1-AS1." (PMID 34811636, 2022). "lncRNA RHPN1-AS increased cell proliferation and invasiveness via regulation of miR-625/REG3A in glioma cells." (PMID 32322669, 2020).
injury (2 papers, 2016 to 2025). Damage inflicted on the body as the direct or indirect result of an external force, with or without disruption of structural continuity. "A second approach has explored recombinant human REG3A protein (ALF 5755) in the treatment of acute liver injury." (PMID 40723277, 2025). "Here we show that the antimicrobial protein REG3A controls TLR3-mediated inflammation after skin injury." (PMID 27830702, 2016). "Taken together, these findings support our discovery that REG3A/ RegIIIγ is important for the control of inflammation after skin injury." (PMID 27830702, 2016).
pancreatic adenocarcinoma (2 papers, 2019). "Patients with Reg3A levels ≥20 μg/ml in pancreatic juice were 21.9 times more likely to have pancreatic adenocarcinoma than those with levels <20 μg/ml." (PMID 31921694, 2019). "The binding of REG3A to the epidermal growth factor receptor (EGFR) was suggested given that the two moieties colocalize upon immunostaining of SW1990 pancreatic adenocarcinoma cells and EGFR/REG3A complexes are detected by co-immunoprecipitation." (PMID 31696115, 2019).
periodontal disease (2 papers, 2020 to 2025). "The early detection of Reg3A/G in urine or blood may prove useful for the prevention of cancer in patients with periodontal diseases." (PMID 33027970, 2020).
Stroke (2 papers, 2023 to 2024). Sudden impairment of blood flow to a part of the brain due to occlusion or rupture of an artery to the brain. "In conclusion, REG3A could be promising as a biomarker to prognosticate stroke outcomes and stratify high-risk groups following acute ischemic stroke." (PMID 39337456, 2024). "While REG3A has been reported to be neuroprotective during brain injury, our findings that increased levels of REG3A predict mortality during MT suggest a potentially detrimental role during stroke." (PMID 39337456, 2024). "Limited data have examined REG3A in the context of stroke pathology; however, increased REG3A has previously been identified as a biomarker in inflammation-driven pathologies such as GVHD and gastrointestinal carcinomas." (PMID 39337456, 2024). "As far as ELVO stroke subjects, REG3A has yet to be examined in context of mortality, but given its involvement as a biomarker in other disease states, it is a strong candidate for further study as a predictor of stroke outcomes." (PMID 39337456, 2024).
acute leukemia (1 paper, 2024). A clonal (malignant) hematopoietic disorder with an acute onset, affecting the bone marrow and the peripheral blood. "We investigated quantitative markers of mucositis including citrulline, CCL20 and REG3α in children with acute leukemia at the onset of fever." (PMID 37919603, 2024).
bladder cancer (1 paper, 2025). "Similarly, in bladder cancer, elevated urinary levels of REG3A have been reported in patients with advanced disease stages." (PMID 40723277, 2025). "Furthermore, REG3A shows promising utility as a urinary biomarker in bladder cancer." (PMID 40723277, 2025).
cardiac hypertrophy (1 paper, 2018). "The role if any played by DNER, REG3A, and IRX1 to diastolic dysfunction and cardiac hypertrophy is not reported, although genetic variants of the IRX1 gene were recently reported to contribute to the pathogenesis of congenital heart disease." (PMID 29556499, 2018).
colon adenocarcinoma (1 paper, 2016). "To determine REG3A expression in CRC, we re-analyzed microarray data from ArrayExperss (Access id: GSE33113) and The Cancer Genome Atlas (TCGA) for the colon adenocarcinoma (COAD) dataset." (PMID 26646797, 2016).
COVID-19 (1 paper, 2021). A disease caused by infection with severe acute respiratory syndrome coronavirus 2. "We also measured the epithelial cell–derived biomarkers S100A8, regenerating islet-derived protein 3 alpha (REG3A), and IL-1α and found both S100A8 and REG3A levels to be modestly increased in COVID-19 patients relative to HVs across all severity categories." (PMID 33232303, 2021).
diabetic retinopathy (1 paper, 2023). "In conclusion, we found elevated levels of Reg-3a, RBP-4, elafin and ZAG in advanced stages of diabetic retinopathy." (PMID 37883447, 2023). "Higher levels of pro-inflammatory proteins, Reg-3a and RBP-4, might contribute to the pathogenesis of diabetic retinopathy, as the parallel increased concentrations of anti-inflammatory molecules elafin and ZAG might indicate a compensatory mechanism." (PMID 37883447, 2023).
Fever (1 paper, 2024). Body temperature elevated above the normal range. "We found significant differences in citrulline, REG3α, and CCL20 in patients with BSI, indicating more severe intestinal mucositis in BSI-related fever episodes, emphasizing the serious implications of bacterial translocation through an injured intestinal epithelium." (PMID 37919603, 2024).